METTL3 (methyltransferase 3, N6-adenosine-methyltransferase complex catalytic subunit)
Diseases named in the same sentence as METTL3 in open-access papers (continued):
Sharing a sentence is not in itself a finding about the gene and the disease.
allergic asthma (5 papers, 2023 to 2025). A asthma with a basis in a pathological type I hypersensitivity reaction. "Mettl3-deficient myeloid cells promote Th2 cell response and aggravate airway inflammation in a mouse allergic asthma model by enhancing M2 macrophage activation." (PMID 37957139, 2023). "We detected a robust decrease of YTHDF3 levels in METTL3-deficient macrophages, and in monocyte-derived macrophages from children with allergic asthma." (PMID 37957139, 2023). "We observed that Ptx3 deficiency markedly attenuated Mettl3 knockout-induced airway inflammation in allergic asthma by suppressing M2 macrophage activation, but the effect of PTX3 on the other cells in vivo can not be excluded." (PMID 37957139, 2023). "Together, these data suggest a possible association between the severity of childhood allergic asthma and a decreased METTL3 expression in monocyte-derived macrophages." (PMID 37957139, 2023). "Current research demonstrates that METTL3 plays a protective role in allergic asthma by suppressing Th2 immune responses." (PMID 41515964, 2025). "To investigate the relevance of m6A modifications in myeloid cell-mediated allergic asthma, we first crossed Mettl3fl/fl mice with Lyz2-Cre mice to ablate Mettl3 in the myeloid compartment, including macrophages and neutrophils." (PMID 37957139, 2023). "Silencing Ptx3 significantly alleviated allergic inflammation in Mettl3 KO mice, whereas higher PTX3 expression in plasma was positively associated with airway inflammation in childhood allergic asthma." (PMID 37957139, 2023). "Here we show that m6A methyltransferases METTL3 is expressed at a low level in monocyte-derived macrophages from childhood allergic asthma patients." (PMID 37957139, 2023). "Here, we report a direct correlation between the decreased expression of METTL3 in monocyte-derived macrophages and the severity of childhood allergic asthma." (PMID 37957139, 2023). "We then sensitized WT and Mettl3 KO mice with cockroach extract (CRE) to induce mouse allergic asthma model." (PMID 37957139, 2023). "In brief, METTL3 was lowly expressed in monocyte-derived macrophages from childhood allergic asthma, while an inverse correlation between METTL3 expression and disease severity was identified." (PMID 37957139, 2023). "Some studies indicate that METTL3 may exacerbate allergic asthma by suppressing M2 macrophage activation through the PI3K/AKT and JAK/STAT6 pathways." (PMID 41515964, 2025). "Finally, METTL3 modulates allergic asthma by regulating M2 macrophage promotion mediated by the PI3K‐AKT and JAK‐STAT6 signaling pathways." (PMID 41316520, 2025). "While it shows protective effects in Th2-dominant allergic asthma, METTL3 may also contribute to disease exacerbation under certain inflammatory or remodeling conditions, emphasizing the need for cell type– and disease endotype–specific therapeutic targeting." (PMID 41515964, 2025). "In allergic asthma, METTL3 may restrain Th2 responses but amplify tissue injury in severe, neutrophil and NET dominant subtypes." (PMID 41515964, 2025). "Notably, METTL3 promotes M2 macrophage activation via regulating the PTX3-STX17 axis, thereby identifying METTL3 as a potential target for controlling allergic asthma." (PMID 39416774, 2024). "Interestingly, we noted that PTX3 levels exhibited the inverse correlation with METTL3 in monocyte-derived macrophages from childhood allergic asthma patients." (PMID 37957139, 2023). "Similarly, METTL3 expression was lower in primary monocyte-derived macrophages of childhood allergic asthma patients than in normal controls." (PMID 37957139, 2023). "We next verified that, compared to 50 normal controls, the abundance of METTL3, METTL14, and YTHDF3 was significantly decreased in PBMCs derived from 55 childhood allergic asthma patients, recruited from the Children’s Hospital of Fudan University." (PMID 37957139, 2023).
asthenozoospermia (5 papers, 2016 to 2024). "METTL3 has been shown to affect the differentiation of spermatogonia and the initiation of meiosis associated with asthenospermia." (PMID 34315853, 2021). "Notably, increased expression of METTL3 is a risk factor for asthenozoospermia because it reduces sperm motility, and subsequently triggers the onset and progression of this condition." (PMID 38332508, 2024). "Our data suggested that the increased m6A contents in asthenozoospermia patients might be caused by the upregulation of methyltransferase encoding genes, particularly METTL3." (PMID 27072590, 2016). "Therefore, METTL3 could serve as a promising diagnostic biomarker and therapeutic target for asthenozoospermia in a clinical setting." (PMID 38332508, 2024). "In humans, high-level m6A can impede sperm motility, according to a study on asthenozoospermia, which also reveals that METTL3 plays an important role in the dynamic modulation of m6A in patients with this condition." (PMID 38937660, 2024). "In summary, we first reported that methyltransferases (METTL3 and METTL14), particularly METTL3, play key roles in the dynamic modification of m6A in asthenozoospermia patients and that increased m6A can impair sperm motility." (PMID 27072590, 2016). "Our results demonstrated that METTL3 played a major role in altering the contents of m6A in asthenozoospermia patients and influenced fertility." (PMID 27072590, 2016). "Asthenozoospermia patients showed significantly higher mRNA expression levels of the methyltransferases, including METTL3 (p = 0.016) and METTL14 (p = 0.025) compared to the healthy controls." (PMID 27072590, 2016). "One study revealed that the expression of METTL3 mRNA in patients with asthenozoospermia was significantly higher than that in controls, which impacts sperm motility and constitutes a detrimental role for asthenozoospermia." (PMID 38332508, 2024). "Therefore, the present work aimed to review studies that have investigated the functions of METTL3 in the reproductive system (including spermatogenesis, follicle development, gametogenesis, reproductive cancer, asthenozoospermia and assisted reproduction failure)." (PMID 38332508, 2024). "The mRNA expression of METTL3 and METTL14 was higher in the asthenozoospermia group than that in the control group." (PMID 38937660, 2024). "It was reported that m6A methylation levels and the expression of METTL3 and METTL14 were up-regulated in semen samples of patients with asthenozoospermia." (PMID 36290597, 2022). "We found that m6A content (p = 0.033) and the mRNA expression of METTL3 (p = 0.016) and METTL14 (p = 0.025) in asthenozoospermia patients were significantly higher than those of controls." (PMID 27072590, 2016). "However according to another study, METTL3, not ALKBH5, is crucial for human male infertility, particularly in the case of asthenozoospermia." (PMID 38937660, 2024).
bladder tumor (5 papers, 2020 to 2024). "For comprehensive understanding of the internal regulatory mechanisms that Mettl3 mediated bladder tumor angiogenesis, we utilized immunostaining to detect and localize the angiogenesis-related factors in vivo." (PMID 33681207, 2021). "Bladder tumor size was obviously decreased after inducible knockout of Mettl3 in K14+ CSCs." (PMID 33681207, 2021). "Overexpression of METTL3 significantly promotes the growth and invasion of bladder tumor cells." (PMID 32765970, 2020). "Additionally, bladder tumor grading described Mettl3 as a driving factor of cancer progression." (PMID 33681207, 2021). "However, some m6A regulators, including METTL3, RBM15B, YTHDF1, YTHDF2, and IGFBP3, were significantly overexpressed in bladder tumors, and some m6A regulators, including METTL14, METTL16, ZC3H13, and YTHDF3, were markedly downregulated in bladder tumors." (PMID 35004726, 2021).
cutaneous squamous cell carcinoma (5 papers, 2020 to 2025). "The HPV vaccine enhances the sensitivity of anti-PD-1 treatment by down-regulating METTL3 in cutaneous squamous cell carcinoma." (PMID 38030537, 2024). "Increased METTL3-mediated m6A promotes the upregulation of p63 and K14, the downregulation of K10, and cell proliferation in cutaneous squamous cell carcinoma." (PMID 37891533, 2023).
epilepsy (5 papers, 2024 to 2025). A brain disorder characterized by episodes of abnormally increased neuronal discharge resulting in transient episodes of sensory or motor neurological dysfunction, or psychic dysfunction. "Changing the levels of m6A-related enzymes including METTL3 has shown in experimental models of epilepsy that this influences seizure susceptibility and neuronal excitability." (PMID 40530256, 2025). "The m6A methyltransferase METTL3/14 (RNA methyltransferase like 3/14), known as the m6A “writer”, is implicated in epilepsy." (PMID 40534269, 2025). "Studies have shown that m6A-related enzymes, such as METTL3, FTO, and ALKBH5, influence epilepsy progression through their effects on gene expression linked to neuronal excitability, synaptic transmission, and oxidative stress." (PMID 40624693, 2025). "For instance, FTO downregulation promotes neuronal damage and exacerbates epilepsy progression, while METTL3 inhibition can reduce neuronal injury." (PMID 40624693, 2025). "Overall, in both mouse and human epilepsy, there are changes in the abundance of enzymes regulating m6A (notably METTL3 in both mouse and human and FTO and ALKBH5 in human TLE), although no gross changes in m6A were detectable using colorimetric assays." (PMID 40693462, 2025). "Activation of METTL3‐mediated downregulation of Vim expression attenuates hippocampal neuronal damage and apoptosis and prevents epilepsy progression." (PMID 39006762, 2024). "DNA/RNA methylation through the DNMT1/3A and METTL3/METTL14 pathway might be therefore a potential target of VNS therapy for the treatment of epilepsy." (PMID 40534269, 2025). "METTL3 has been reported to be involved in the regulation of epilepsy." (PMID 39006762, 2024). "We conclude that VNS reduces the number of SRSs in a rat model of epilepsy, concurrently reducing the expression of 5‐mC, DNMT1, DNMT3A, METTL3, and METTL14, as well as the increase of 5‐hmC." (PMID 40534269, 2025). "Vagus nerve stimulation (VNS) reduces the number of SRSs in rats with epilepsy with concomitant decrease of 5‐mC, DNMT1, DNMT3A, METTL3, and METTL14, as well as increase of 5‐hmC." (PMID 40534269, 2025). "Moreover, a research study demonstrated that m6A modification is highly involved in epilepsy through the regulation of gene expression involving a transcription factor, SRF, and METTL3." (PMID 40530256, 2025).
gastrointestinal stromal tumor (5 papers, 2023 to 2025). "For example, METTL3 confers imatinib resistance, and high levels of METTL3 could predict the poor prognosis of patients with gastrointestinal stromal tumors (GISTs)." (PMID 36835633, 2023). "In addition, METTL3 induces autophagy to enhance the imatinib resistance in gastrointestinal stromal tumor cells by upregulating USP13 expression and promoting deubiquitination of ATG5." (PMID 37996892, 2023). "Elevated METTL3 levels were detected in imatinib‐resistant gastrointestinal stromal tumor (GIST) cells and tissue samples which insert the m6A modification to the 5′‐UTR of its downstream target MRP1 mRNA." (PMID 39661414, 2024). "In imatinib-resistant gastrointestinal stromal tumors, ETV1 activates METTL3 transcription and further promotes m6A modification mediated by METTL3 at the 5’UTR of MRP1 RNA, stimulating translation of MRP1 RNA and promoting imatinib resistance in tumor cells." (PMID 37996892, 2023). "For example, METTL3-mediated stabilization of USP13 RNA has been shown to promote autophagy and imatinib resistance in gastrointestinal stromal tumors, while in HCC, METTL3 has been reported to regulate cancer stem cell properties and contribute to lenvatinib resistance via FZD10." (PMID 39472692, 2025).
intracerebral hemorrhage (5 papers, 2024 to 2026). A cerebrovascular disorder characterized by bleeding into one or both cerebral hemispheres including the basal ganglia and the cerebral cortex. "METTL3 mRNA expression was higher in mice with collagenase-induced intracerebral hemorrhage than in controls, whereas WTAP, FTO and ALKBH5 expression was lower in mice with collagenase-induced intracerebral hemorrhage than in controls." (PMID 41601663, 2026). "Roles for Mettl3 have been reported in intracerebral haemorrhage and ischaemic stroke, including neonatal HIE, where Mettl3 was shown to contribute to microglial activation and inhibit microglial pyroptosis." (PMID 41488750, 2025). "Cell experiments revealed that the inhibition of METTL3 or knockdown of ETV4 can significantly alleviate neuroinflammation and brain tissue damage caused by intracerebral hemorrhage, suggesting a causal relationship between this regulatory axis and disease progression." (PMID 41601663, 2026). "Moreover, methyltransferase-like 3 (METTL3) lactylation enhances METTL 3 protein stability in intracerebral hemorrhage." (PMID 38439082, 2024). "Furthermore, a study on intracerebral hemorrhage indicated that METTL3 induced the development of ferroptosis by regulating the m6A level of TFRC mRNA." (PMID 38221933, 2024). "Furthermore, the protein abundance of METTL3 was also higher and that of METTL14 was lower in mice with collagenase-induced intracerebral hemorrhage than in controls." (PMID 41601663, 2026). "Recent studies have demonstrated that in an intracerebral hemorrhage (ICH) model, the lactylation of methyltransferase-like protein 3 (METTL3) was significantly upregulated, leading to enhanced stability and increased expression of the METTL3 protein." (PMID 40226593, 2025).
ischemic stroke (5 papers, 2022 to 2025). A stroke disorder caused by obstruction of blood flow to the brain, due to thrombotic (local blood clot formation) or embolic (due to a blood clot or other material traveling from another site) event. "Our results confirm that the pharmacological activity of berberine in alleviating ischemic stroke is associated with Nampt, and reveal the associated mechanism of METTL3 and NEAT1 from the viewpoint of m6A modification." (PMID 38180752, 2024). "We assessed the possibility that methyltransferase METTL3 is involved in regulating NEAT1 m6A modification in ischemic stroke by MeRIP-qPCR." (PMID 38180752, 2024). "Augmenting METTL3 represents a novel approach to suppress iron-mediated oxidative damage and regulated cell death after ischemic stroke." (PMID 38302612, 2024). "METTL3 and YTHDC1 promote Akt phosphorylation to alleviate ischemic stroke by destabilizing PTEN mRNA." (PMID 38180752, 2024). "Collectively, our findings identified a METTL3/AU020206/YTHDC2/SLC7A11 axis that curbs ferroptotic injury after cerebral I/R and highlight epitranscriptomic modulation of lncRNA stability as a promising therapeutic avenue for ischaemic stroke." (PMID 41154582, 2025).
lentivirus infection (5 papers, 2018 to 2025). Virus diseases caused by the Lentivirus genus. "Ectopic expression of METTL3 mediated by lentivirus infection leads to disorganized structure of both Purkinje and glial cells." (PMID 29855379, 2018). "Similarly, we found that Mettl3 knockdown by lentivirus infection markedly upregulated Fem1b mRNA level." (PMID 40016417, 2025). "The results of METTL3 lentivirus infections of primary adipocytes were similar." (PMID 37569302, 2023). "Then, we transduced METTL3 shRNA into SCAPs to inhibit METTL3 expression with lentivirus infection." (PMID 37323630, 2023). "The efficiency of lentivirus infection was examined by observing green fluorescence of GFP, and the efficiency of METTL3 knockdown was detected by western blotting." (PMID 37056933, 2023).
liver diseases (5 papers, 2020 to 2025). "Portal hypertension (PHT)‐induced mouse models in METTL3 mutant or NLRP3‐deficient littermates were established, and nude mouse gastric graft tumour models with relevant inhibitors were generated." (PMID 38616702, 2024). "As a core m6A methyltransferase, METTL3 mediates the m6A methylation process in liver diseases." (PMID 40959279, 2025).
malignant glioma (5 papers, 2019 to 2021). A grade III or grade IV glioma arising from the central nervous system. "The elevated METTL3 expression was associated with the clinical aggressiveness of malignant gliomas." (PMID 34721530, 2021). "Transcriptome studies showed that impaired METTL3 methylation results in the generation of PTCs in the mRNAs of several SRSFs, contrary to the existing scenario in malignant gliomas, which are associated with elevated expression of METTL3 and lower expression levels of SRSFs NMD spliced forms." (PMID 33926465, 2021). "However, a controversial study showed that elevated expression of METTL3 is associated with the clinical aggressiveness of malignant gliomas, METTL3 knockdown or overexpression of dominant-negative mutant METTL3 suppressed the growth and self-renewal of GSC." (PMID 33611339, 2021).
nonalcoholic fatty liver disease (5 papers, 2022 to 2025). "Nuclear WATP or METTL3 downregulation has been linked to NASH, and hepatic Wtap or Mettl3 deletion enhances liver damage, nonalcoholic fatty liver disease, and HCC initiation, whereas WTAP and METTL3 are abnormally elevated in HCC, promoting HCC progression." (PMID 37777158, 2023). "In nonalcoholic fatty liver disease (NAFLD)-associated HCC, cancer cells show an elevated expression of N6-methyladenosine (m6A)-methyltransferase catalytic subunit (METTL3)." (PMID 40270603, 2025). "METTL3 is a key regulator of liver function and homeostasis, and increasing evidence suggests that METTL3 is critical for the development and progression of non-alcoholic fatty liver disease (NAFLD)." (PMID 41194259, 2025).
pancreatic adenocarcinoma (5 papers, 2021 to 2023). "For instance, METTL3-mediated m6A modification on the 5’UTR of NUCB1 (encoding a calcium-binding protein) mRNA via YTHDF2 (YTH N6-methyladenosine RNA binding protein 2) reader protein in pancreatic adenocarcinoma was associated with poor prognosis." (PMID 36977668, 2023). "In conclusion, METTL3 regulates the cell cycle in pancreatic adenocarcinoma cells through the methylation of the PLK1 3′UTR, and its disruption of homeostasis increases cell death via replication stress and may be a new target for radiosensitization." (PMID 35773310, 2022). "However, the functional group of genes whose expression is directly regulated by METTL3 in pancreatic adenocarcinoma and the detailed mechanisms are still unknown." (PMID 35773310, 2022). "In pancreatic adenocarcinoma (PAAD), cigarette smoke condensate induces hypomethylation of METTL3 promoter and excessively maturates miR‐25 to promote cancer progression." (PMID 36260366, 2023).